ALB (albumin)
Diseases named in the same sentence as ALB in open-access papers (continued):
Sharing a sentence is not in itself a finding about the gene and the disease.
Hypoalbuminemia (continued). "HES is not a replacement for albumin and in patients with severe hypoalbuminemia, natural colloids (such as plasma products or albumin) should be considered." (PMID 34277747, 2021). "Based on albumin levels (< 35 or ≥ 35 g/L), patients were divided into two groups; 501 (34.6%) had hypoalbuminemia and 948 (65.4%) did not have hypoalbuminemia." (PMID 34961476, 2021). "Hypoalbuminemia in the presence of protein malnutrition can be attributed to compromised hepatic synthesis of albumin due to a lack of amino acid availability." (PMID 34920728, 2021). "In contrast, serum albumin levels in the non-COVID-19 group indicated hypoalbuminemia (mean albumin serum 2.5 ± 0.7 g/dL) and were lower than the COVID-19 group (mean albumin serum 3.2 ± 0.5 g/dL; p = 0.027)." (PMID 33585030, 2021). "Even in the presence of severe hypoalbuminemia, albumin infusion was not part of the routine therapy of decompensated liver cirrhosis." (PMID 34281177, 2021). "Lack of return of filtered fluid and albumin in the form of interstitial washdown to the plasma would promote the development of hypovolemia, extravascular edema, and hypoalbuminemia." (PMID 34448075, 2021). "However, the magnitude of change in albumin status depends on the duration of ONS feeding, severity of hypoalbuminemia, chronic inflammation and hydration status, not withstanding the pro-inflammatory nature of dialysis treatment." (PMID 34977109, 2021). "Albumin infusion as a therapy for decompensated cirrhosis and severe hypoalbuminemia, even if largely used, is not yet included in the actual guidelines." (PMID 34281177, 2021). "HDx resulted without a significant decrease of albumin in 12 out of the total 19 studies performed, and with a significant removal in 6 studies although it was not registered any clinical signs of hypoalbuminemia." (PMID 34073439, 2021). "Other indications representing less than 5% of the albumin use included acute respiratory distress syndrome (ARDS), paracentesis, hyponatremia, hypervolemia or edema, cirrhosis, hepatorenal syndrome, respiratory failure, and hypoalbuminemia in liver disease." (PMID 34613990, 2021). "The study concluded that albumin administration in the early stage of postoperative hypoalbuminemia is not beneficial in correcting hypoalbuminemia or in improving clinical outcomes." (PMID 34067286, 2021). "We designed the current randomized multicenter trial to assess whether standard care plus albumin therapy will increase the proportion of clinically stable patients at day 5 of admission compared to standard care alone in patients with CAP and hypoalbuminemia." (PMID 32819439, 2020). "While we do not recommend albumin supplementation for patients with hypoalbuminemia for the prevention of influenza A, we recommend that measures such as droplet precautions with single room isolation be mandatory." (PMID 33213361, 2020). "The occurrence of hypoalbuminemia can be plausibly explained by the fact that albumin is a negative acute phase reactant, not a consequence of liver dysfunction." (PMID 33194489, 2020). "While Low‐MP did not improve hypoalbuminemia, High‐MP, Pio, and Pio + Low‐MP all improved albumin levels versus no treatment (p < .05)." (PMID 32776495, 2020). "However, after pre- and postsurgical albumin infusion or administration of a normal protein diet, the levels of TNF-α, IL-1, IL-6, CRP, and MMP-8 were significantly reduced relative to the hypoalbuminemia group." (PMID 32518615, 2020). "The traditional GPS is derived by allocating one point each for elevated CRP (>10 mg/L) and hypoalbuminemia (serum albumin < 35 g/L), so that patients with both, one, or none of these conditions would have a score of 2, 1, or 0, respectively." (PMID 31998420, 2020). "Despite the prognostic importance of hypoalbuminemia, the prognostic implication of a change in albumin levels has not been fully investigated during hospitalization in patients with acute decompensated heart failure (ADHF)." (PMID 33370299, 2020).
Hypoalbuminemia (continued). "In our study, indomethacin caused a marked decrease in albumin and total protein levels in serum without affecting serum biochemical markers of liver function, but GMP treatment prevented hypoalbuminemia and hypoproteinemia." (PMID 32443501, 2020). "Hypoalbuminemia is an inflammatory surrogate rather than nutritional marker among these patients with cancer, and serum albumin reflects the inflammatory and nutritional status of patients." (PMID 33585198, 2020). "In our study hypoalbuminemia was not predictive of toxicity, but it is important to note that data on albumin levels were missing in 30% of our cases." (PMID 32122396, 2020). "Despite the prognostic importance of hypoalbuminemia, the prognostic implication of a change in albumin levels has not been fully investigated." (PMID 33370299, 2020). "Because PNI consists of albumin and lymphocyte levels, low PNI means hypoalbuminemia and lymphocytopenia, which may contribute to tumor development and progression." (PMID 33129309, 2020). "On the contrary, serum albumin is a negative acute-phase protein, and the intensity of inflammation response correlates with the degree of hypoalbuminemia." (PMID 33324592, 2020). "Age, body mass index, preoperative platelet counts and serum albumin concentrations, and rate of hypoalbuminemia differed significantly in the PPC and non-PPC groups." (PMID 31547129, 2019). "Hypoalbuminemia is frequently observed during acute disease state, as albumin is a negative acute-phase protein." (PMID 30745875, 2019). "A European survey on use of albumin in cirrhosis suggested that albumin was mainly employed for preventing PPCD and renal failure and treating type-1 HRS, ascites, non-SBP bacterial infections, severe hyponatremia (<125mmol/L), HE, and hypoalbuminemia." (PMID 31596729, 2019). "Moreover, there was a remarkable decrease in serum albumin in AN rats, and TEA improved hypoalbuminemia." (PMID 31191310, 2019). "In models 2 and 3 of Cox proportional hazard model analysis, albumin violated the proportional hazard assumption and stratified analysis with hypoalbuminemia (No vs Yes) was performed." (PMID 31863079, 2019). "Difference in postoperative complications (55.6% and 37.8% of patients with hypoalbuminemia and normal serum albumin levels, respectively) was not statistically significant (p = 0.345)." (PMID 31468203, 2019). "Curiously, our female patient that presents lower limb lymphedema, has no albumin alteration in a Norwegian female patient, undermining the theory that lymphedema was secondary to hypoalbuminemia." (PMID 30039206, 2018). "The hematocrit and albumin levels of participants had little variability, with only one subject being anemic, and none having hypoalbuminemia." (PMID 29415014, 2018). "Albumin has been considered a negative acute-phase protein, since its serum concentration is prone to decrease in trauma and sepsis, and hypoalbuminaemia has proven to be a marker of poor prognosis in different clinical settings, including bacteremia." (PMID 29479635, 2018). "The two most common inappropriate uses of albumin in the post-intervention period were management of edema in patients without severe hypoalbuminemia (24.58%) and a component of parenteral nutrition (19.87%)." (PMID 30355286, 2018). "Regarding protein alterations, the severity of clinical score has been correlated with an increase of total proteins and a decrease in albumin concentration and therefore, hypoalbuminemia and hyperproteinemia are negative prognosis markers of CanL." (PMID 30237985, 2018). "Yet, the direct effects of in-vivo oxidized albumin and the link among specific albumin modifications, hypoalbuminemia and endothelial functions, have not been explored." (PMID 28542419, 2017). "Low preoperative pre-albumin level but not preoperative hypoalbuminemia is a negative independent prognostic factor for survival outcome in patients with UTUC undergoing radical nephroureterectomy." (PMID 27906675, 2017).
Hypoalbuminemia (continued). "In our multivariable analysis, low pre-albumin level was an independent predictor in UTUC patients but not hypoalbuminemia." (PMID 27906675, 2017). "PFS and OS were compared between patients with post-treatment hypoalbuminemia (post-treatment albumin level <36.4 g/L) and those with normal post-treatment albumin level (albumin level ≥36.4 g/L)." (PMID 28521783, 2017). "If hypoalbuminemia indicates immunological deterioration in patients with decompensated LC, patients who are positive for ISH may be required to receive albumin infusions early in addition to antibiotics." (PMID 29041907, 2017). "Nephrotic syndrome without hypoalbuminemia (23.6%) was the most prevalent reason for albumin misuse and internal ward was the most consuming unit." (PMID 28979337, 2017). "Nephrotic syndrome without hypoalbuminemia (23.6%) was the most prevalent reason for albumin misuse." (PMID 28979337, 2017). "Whilst hypoalbuminemia (absolute serum values) is well established for nutritional assessment and prediction of complications, the early postoperative albumin decrease (delta from baseline) has not yet been implemented into clinical management." (PMID 26880899, 2016). "In our study, the mean serum albumin level of the group with effusion was 3.11 ± 0.51 g/dL, which was lower than that of the group without effusions, and 45 patients (48.4 %) had hypoalbuminemia (≤3.0 g/dL)." (PMID 27287396, 2016). "However, previous studies have found that hypoalbuminemia may be used as an effective indicator of up-regulated cancer-related inflammatory response, which is mainly attributed to the cytokine-induced suppression of albumin synthesis and increased albumin degradation." (PMID 26966671, 2016). "Albumin administration for critically ill patients did not improve mortality or morbidity even for hypoalbuminemia patients." (PMID 26768898, 2016). "Albumin has an important role in transporting cholesterol to HDL and thus hypoalbuminemia may contribute to the high prevalence of low HDL observed in patients with CKD." (PMID 27005668, 2016). "In the class of albumin <35 g/l, only 44.4 % (16/36) patients had the FBG > 90 mg/dL, but in the class of albumin >40 g/l, almost 76.1 % (105/138) patients had the FBG > 90 mg/dL, and both hypoalbuminaemia and low FBG level were proved to be worse survival factors." (PMID 28003023, 2016). "By reviewing medical records of typical cases, we realized that cases with hypoalbuminemia and high NGAL levels may experience elevation in serum albumin levels after recovery from infection (or inflammatory disorders)." (PMID 26161663, 2015). "We consider that hypoalbuminemia resulted from increased CRP, which can be explained by the following: inflammatory cytokines decrease the synthesis of constitutive proteins, such as serum albumin, and increase its degradation." (PMID 26530188, 2015). "Levels of albumin are decreased in patients with inflammatory states, thus it's not clear to what extent hypoalbuminemia is due to malnutrition or simply a reflection of inflammatory states." (PMID 26491522, 2015). "Albumin is a negative acute phase protein and inflammatory hypoalbuminemia can develop after on-going inflammatory states and is usually expected to be mild." (PMID 25880447, 2015). "In most cases, albumin administration seemed to be used mainly for resuscitation and volume expansion rather than correcting hypoalbuminemia." (PMID 26557421, 2015). "A benign form of albuminuria, that does not lead to hypoalbuminemia, has been proposed as a result of inhibition of kidney specific degradation of filtered albumin." (PMID 26010895, 2015). "The significantly higher concentration of serum albumin, which contributed to higher SIG, might have reduced the alkalinizing effect of hypoalbuminemia and contributed to acidosis in the surviving AKI patients." (PMID 25162029, 2014).
Hypoalbuminemia (continued). "Current evidence regarding the beneficial or deleterious effect of albumin in this context is inconclusive, especially in surgical patients and those without hypoalbuminemia." (PMID 25394836, 2014). "Serum albumin is a negative acute-phase protein; thus, the degree of hypoalbuminemia in critically ill patients correlates with the intensity of the inflammatory response triggered by infection." (PMID 23555017, 2013). "In the present study, although hypoxemia and hypoalbuminaemia were not identified as independent predictors of mortality by multivariate analysis, patients who died tended to present lower levels of albumin and pO2." (PMID 21970460, 2011). "Fever was also more common in those aged less than 65 years (54% vs. 23%, p < 0.001), without underlying co-morbidities (40% vs. 24%, p = 0.017), or without hypoalbuminemia (defined as a serum level of albumin less than 3.5 g/dL) (42% vs. 26%, p = 0.049)." (PMID 21338482, 2011). "In the present study, there was only a weak relationship between albumin concentrations and tumour volume, and therefore the prognostic value of hypoalbuminaemia would not appear to be primarily dependent on tumour burden." (PMID 15213726, 2004). "Albumin non-significantly declined over time, with hypoalbuminemia observed across all groups by 8 M. At 3 M, the FA ratio was elevated in OVXDS [11.2:5.9, 8.32 ± 1.38 μmol/g] vs. Control [7.4:3.5, 5.24 ± 1.13 μmol/g], p < 0.01; this persisted at 8 M (p < 0.01)." (PMID 41228426, 2025). "Albumin levels were within the normal range for the majority of patients (96.4%, mean 3.92 ± 0.32 g/dL), one patient (3.6%) had elevated albumin (7.1 g/dL), and no cases of hypoalbuminemia were observed." (PMID 41010736, 2025). "However, albumin molecules carry a net negative charge, which means that changes in their concentration can affect AG outcomes in patients with hypoalbuminaemia." (PMID 40007853, 2025). "For infants with preoperative hypoalbuminemia, treating and/or preventing potential protein malnutrition or heart failure, rather than supplementing albumin, may have a greater impact on improving postoperative outcomes." (PMID 39896721, 2025). "Four days prior to admission, she had been diagnosed with NS at an external hospital, marked by hypoalbuminemia (Albumin 17.1 g/L), hyperlipidemia (total cholesterol 15.78 mmol/L), and significant proteinuria (urinary albumin ++++), in the absence of hematuria." (PMID 40980126, 2025). "Since albumin is negatively charged that will lead to a decrease in AG,hypoalbuminemia may lead to false negative AG results, affecting the accurate judgment of the results." (PMID 40680007, 2025). "However, this patient had proteinuria without hypoalbuminemia until later in her hospitalization, and serum albumin at its lowest was 3.3 mg/dL." (PMID 41246570, 2025). "AKI patients with mild-to-moderate hypoalbuminemia may still respond to FST without albumin infusion, although response rates decline with the increasing severity of hypoalbuminemia." (PMID 41291529, 2025). "Plasma albumin concentration was normal in 11 dogs (65%), mildly decreased in 4 dogs (23%), and moderately decreased in 2 dogs (12%), and none of the dogs had severe hypoalbuminemia." (PMID 40872702, 2025). "The same was observed for serum albumin—some patients had hypoalbuminemia, and some did not." (PMID 40843703, 2025). "This variability may be attributed in part to differences in the thresholds used to define hypoalbuminaemia (albumin less than 25–35 g/l), with no clear consensus on the most clinically relevant cut-off40,42." (PMID 39213130, 2024). "Subgroup analysis was further performed in population (surgical vs. medical), received procedure or not (PCI vs. non-PCI), baseline CKD (including or excluding CKD population), serum albumin level (hypoalbuminemia vs. not), and used AKI criteria (KDIGO vs. other)." (PMID 38671543, 2024).
Hypoalbuminemia (continued). "Hypoalbuminemia also leads to hepatotoxicity among TB patients due to triggering inflammatory responses such as tumor necrosis factor (TNF) and interleukin (IL)-6 in TB patients, which leads to increased vascular permeability, increasing degradation, and decreasing synthesis of albumin." (PMID 39502524, 2024). "However, most studies have evaluated serum albumin levels rather than hypoalbuminemia as a predictor of mortality in older adult patients." (PMID 39882120, 2024). "The patient was maintained on enalapril (6 mg/day, 0.15 mg/kg), and her latest follow-up at the age of 12 years revealed preserved kidney function (serum Cr, 0.88 mg/dL; eGFR, 58.8 mL/min/m2) and mild proteinuria (UPCR, 0.40 g/gCr), without hypoalbuminemia (serum albumin, 3.8 g/dL) and hematuria." (PMID 39105016, 2024). "While albumin levels did not significantly influence certain parameters, hypoalbuminemia may serve as an indicator of severity and adverse prognosis in sepsis, emphasizing the need for further research and tailored interventions." (PMID 38826606, 2024). "Additionally, compared to the normal albumin level group, the hypoalbuminemia group had a higher incidence of POD (p < 0.001), and the incidence of POD increased with the severity of hypoalbuminemia (trend p < 0.001)." (PMID 38420358, 2024). "Due to the high cost of albumin and its lack of essential amino acids, such as tryptophan, it is generally not used to correct nutritional status and is instead reserved for treating severe cases of hypoalbuminemia." (PMID 39766011, 2024). "Similarly, the PK of dalbavancin, oritavancin, tedizolid, and delafloxacin is likely to change significantly in patients with severe hypoalbuminemia (i.e., serum albumin < 2 g/dL), but no data are available from the literature in this clinical context." (PMID 37765112, 2023). "Interestingly, serum-albumin, but not proteinuria levels at baseline correlate with faster recovery of nephrotic range proteinuria or hypoalbuminemia." (PMID 37563703, 2023). "Third, although many previous reports have used a serum albumin level of 3.0 g/dL to define hypoalbuminemia after liver transplantation, it is not clear whether applying the same level for calculating the area under the threshold is appropriate." (PMID 37167307, 2023). "Therefore, hypoalbuminemia can be used as a warning sign for the development of peritonitis in patients undergoing CAPD and immediate intervention is needed to prevent peritonitis when serum albumin levels fall." (PMID 37790129, 2023). "Although the blood albumin concentration was not shown in this study, it was confirmed that the iCa was very strongly correlated with the tCa; we considered that cows with hypoalbuminemia were excluded, and we created an estimation formula to calculate the tCa." (PMID 37885616, 2023). "However, a multicenter randomized controlled trial suggested that albumin infusion as resuscitation for patients with sepsis (with or without baseline hypoalbuminemia) failed to provide survival benefits." (PMID 36337861, 2022). "However, our results showed that only 14.4% (21/146) of the CD inpatients had hypoalbuminemia and no patients had hypo-hemoglobinemia, suggesting that albumin and hemoglobin cannot be used as the only indicator for nutritional assessment." (PMID 36712517, 2022). "Furthermore, there was a steady decline in the albumin rate in all experimental groups, with the four intervals revealing no significant hypoalbuminemia, emphasizing the transitory decrease that was restored at the end of the experiment." (PMID 36290298, 2022). "Further research is needed to delineate the role of albumin levels in patients treated with ICIs in adjuvant settings and patients treated with ICI-based combinations, as well as the possible benefit of therapeutic approaches to improve hypoalbuminemia in ICI-treated patients." (PMID 36533070, 2022).